LEP (leptin)
Diseases named in the same sentence as LEP in open-access papers (continued):
Sharing a sentence is not in itself a finding about the gene and the disease.
cancer (continued). "One of the important mediators between obesity and increased cancer risk is leptin, which is an adipokine whose major functions are regulating appetite and energy homeostasis." (PMID 23425972, 2013). "Associations between the adiponectin-to-leptin ratio and the metabolic syndrome and several cancers (32–, 34) have also been reported, but there is insufficient data thus far to assess the strength of this relationship." (PMID 23967401, 2013). "Similar data have been reported in mice with cancer cachexia, in which severe weight loss is associated with decreased leptin and insulin, whereas resistin remains unchanged." (PMID 23781298, 2012). "Originally known for its role in satiety and weight loss, leptin more recently has been shown to augment tumor growth in a variety of cancers." (PMID 22263109, 2012). "The fact of reducing total daily food intake has been shown to increase the adiponectin:leptin ratio, and it significantly reduces the risk of developing cancer." (PMID 23272114, 2012). "Recall that EE-induced activation of the brain-adipocyte BDNF/leptin axis causes cancer remission and inhibition in mice, and distress reduction lowers the rate of recurrence in breast cancer patients." (PMID 22263109, 2012). "Authors of numerous articles attempt to link blood leptin concentration with the risk of occurrence and the possibility of transformation of various types of cancer." (PMID 22363883, 2011). "A number of studies have examined the possible role of leptin in the pathogenesis of cancer-related weight loss." (PMID 21040518, 2010). "Hypoxia can also upregulate the expression of a cytokine leptin (Ob) - a multifunctional peptide hormone that has been implicated in cancer cell growth, transformation, metastasis and resistance to cancer treatments." (PMID 20569445, 2010). "Clinical studies also assess leptin and adiponectin levels in relation to risk from cancer, as well as mechanistic studies to prove these adipocytokines role in the development of cancer." (PMID 21566743, 2008). "Notably, findings from the prospective, though uncontrolled, LABS study suggest that reductions in insulin, leptin, and ghrelin after bariatric surgery are independently associated with decreased cancer risk." (PMID 41490246, 2026). "Additionally, adipokines released by adipose tissue, including leptin and adiponectin, have been demonstrated to affect tumor behavior, with heightened leptin levels associated with an increased risk and progression of cancer." (PMID 41294697, 2025). "In addition, it is suggested that leptin produced by cancer-associated fibroblasts activates MAPK/ERK1/2 and PI3K/AKT pathways in NSCLC, promoting proliferation and migration of malignant cells." (PMID 41463203, 2025). "Adipocytes can be activated by cancer cells into cancer associated adipocytes (CAAs), which in turn actively support the development and spread of BC by secreting hormones, adipokines (i.e., adiponectin, leptin) and fatty acids." (PMID 41374952, 2025). "Moreover, chronic inflammation within the liver extends its impact by activating pathways like NF-κB, reducing adiponectin while increasing leptin levels, which are implicated in the pathogenesis of cancers." (PMID 40493745, 2025). "Indeed, in the dynamic crosstalk between AT and tumor cells, the leptin/adiponectin ratio has a key role in determining the risk of cancer formation and progression through low‐grade chronic inflammation pathways." (PMID 39806854, 2025). "Interestingly, the PI3K/AKT/MAPK cascade is one of the signal mediators of leptin, adiponectin, and many inflammatory cytokines, and is also a pathway very frequently mutated in human cancers." (PMID 39940361, 2025).
cancer (continued). "Several scientific studies have established a significant association between body fat percentage and cancer risk, increasing insulin resistance, inflammation, and altering leptin levels, inducing changes in the metabolism, and causing an increase in the risk of up to 13 different types of tumors." (PMID 38338203, 2024). "Our findings revealed a significant decrease in adiponectin levels (encoded by ADIPOQ), which are known for their inhibitory effects on cancer, while there was a marked increase in leptin levels (encoded by LEP), known for their growth-promoting effects, in MIIP+/− CM-treated adipocytes." (PMID 38245780, 2024). "Direct leptin stimulation of ECs is critical for the angiogenesis that underlies healthy adipose tissue extension, as well as for angiogenesis and tumor neovascularization in cancers such as glioblastoma in vitro." (PMID 39439572, 2024). "Studies have demonstrated that adults with high body fatness and elevated insulin levels tend to have abnormal serum concentrations of adipokines, with reduced adiponectin and elevated leptin levels, which have been associated with increased risk for adiposity-related cancers." (PMID 39317703, 2024). "Leptin exerts its action by binding its own receptor (ObR), a member of the class 1 cytokine receptor family, which is implicated in several processes linked to cancer progression, including cell proliferation, metastasis, angiogenesis, and chemoresistance." (PMID 37509120, 2023). "Both resistin and leptin can exhibit proliferative, anti-apoptotic, pro-inflammatory effects and stimulate angiogenesis, making them potential diagnostic and prognostic biomarkers for cancer." (PMID 37238197, 2023). "Moreover, studies have shown an additional leptin production site to be present in the form of fibroblasts associated with cancer." (PMID 36900364, 2023). "The mechanisms underlying the role of excess body weight in advanced-stage cancer are thought to be due to higher levels of hormones and growth factors, such as insulin and leptin, and lower levels of testosterone, which may promote carcinogenesis." (PMID 38020965, 2023). "DUET also promoted improvements in levels of CRP and glucose that have been observed in other more intensive weight loss interventions among cancer survivors, though few differences were detected in other biomarkers typically associated with weight loss, i.e., leptin, adiponectin, and insulin." (PMID 36900368, 2023). "Leptin has been linked to aberrant angiogenesis in many types of cancer." (PMID 37686525, 2023). "Moreover, leptin secreted from cancer-associated fibroblasts isolated from NSCLC patients acting in a paracrine way can sustain NSCLC cell proliferation and migration by activating both the PI3K-AKT and MAPK-ERK signaling axes." (PMID 37509120, 2023). "Leptin is associated with carcinogenesis and the progression of various cancers." (PMID 36981858, 2023). "Leptin and adiponectin are most abundant among these and are implicated in cancer development." (PMID 37954072, 2023). "A recent study showed that ObR RNA expression and concomitant leptin secretion is found in cancer-associated fibroblasts (CAFs) and proposed that leptin is integral in mediating the crosstalk between potentially cancerous breast cells and CAFs, causing tumor growth and invasive characteristics." (PMID 36900364, 2023). "Hence, the leptin–adiponectin ratio can be used as an estimator of risk, a diagnostic marker, and a therapeutic strategy in cancers associated with adiposopathy." (PMID 37444627, 2023). "Leptin and adiponectin play important roles in this regulation, with increased leptin and decreased adiponectin being the primary causes of cancer, cardiovascular and metabolic diseases, as well as problems in the gut microbiota and, consequently, mental health as well as immunity." (PMID 37238961, 2023).
cancer (continued). "Consequently, studies underscore the significance of leptin as a potential biomarker for assessing cancer risk, particularly in individuals who are overweight or obese." (PMID 38068717, 2023). "Furthermore, previous studies have found that Leptin levels and expression associated with malignant tumors play a vital role in tumor progression and can be used as a diagnostic and prognostic indicator." (PMID 37542585, 2023). "The other variable in the prognostic test – leptin – has been described in various types of tumor cells, including breast, prostate, colon and endometrium where leptin has been implicated as a growth factor for these cancers." (PMID 36973672, 2023). "Moreover, high levels of serum leptin and low levels of serum adiponectin are independently associated with cancer metastasis risk." (PMID 38239881, 2023). "The value of leptin as part of a cancer diagnostic workup is an interesting avenue to pursue." (PMID 35628271, 2022). "Moreover, the relationship between higher leptin and the risk of metabolic diseases, including cancer, has been revealed." (PMID 35328822, 2022). "Despite the fact that there have been multiple studies revealing higher levels of leptin expression across many cancer tissues/cells, the mechanistic details for the causes of these higher expression levels of leptin in cancer tissues/cells have only been addressed by a few studies." (PMID 35778755, 2022). "Indeed, a series of cytokines, such as leptin, adiponectin and visfatin, have been found in tumor microenvironments and have been implicated in cancer cell growth, apoptosis, invasion, angiogenesis and metastasis." (PMID 36497484, 2022). "The interaction between obese adipocytes and cancer cells can leads to transformation of adipocytes into cancer-associated adipocytes (CAAs) which may promote lymphoma via secreting more leptin and reducing the production of adiponectin." (PMID 35279210, 2022). "The role of leptin in obesity-associated cancers has been previously reviewed." (PMID 36361914, 2022). "The G19A LEP SNP may interfere with various processes such as RNA transcription, translation, and steadiness, thereby changing leptin protein expression and correlating with cancer risk." (PMID 35563103, 2022). "When adipose tissue expands, an imbalance of adipokines secretion may occur and increasing leptin levels contribute to promoting a chronic inflammatory state, which is largely acknowledged as a hallmark of cancer." (PMID 36291602, 2022). "Furthermore, serum levels of leptin are deregulated in metabolic and immune diseases and have been associated with different types of cancers." (PMID 33587254, 2021). "Given the emerging role of adiponectin and leptin as risk biomarkers in cancer and other diseases, implementing laboratory methods could be useful for a personalized risk assessment." (PMID 34209441, 2021). "Genetic variants of the LEP gene in cancer patients have been reported in several studies." (PMID 33799880, 2021). "The LEP G19A polymorphism may alter the transcription of mRNA and the level of LEP was confirmed to be associated with any kind of cancer." (PMID 34868961, 2021). "Studies confirmed that the LEP G19A mutation might reduce mRNA translation with a lower serum level of LEP, which may attenuate the cancer risk as a protective factor." (PMID 34868961, 2021). "Therefore, we conducted this meta-analysis to address this relevance between the LEP G19A polymorphism and cancer risk." (PMID 34868961, 2021). "Several studies have reported that leptin and leptin receptor are implicated in cancer, mainly via the JAK/STAT pathway, which regulates PI3K/AKT3 and ERK1/2 signaling, angiogenic factors (VEGF), systemic inflammation (TNF-α, IL6), and anti-apoptotic proteins (XIAP) expression." (PMID 34356668, 2021).
cancer (continued). "It has been recently demonstrated that leptin can induce autophagy in cancer cell lines from different tissues, suggesting that autophagy could modulate the pro-tumorigenic effects associated with leptin." (PMID 33763424, 2021). "Therefore, we performed a meta­analysis to verify the correlation between the G19A mutation of the LEP gene and susceptibility to cancers." (PMID 34868961, 2021). "In this study, we conducted a meta-analysis to verify whether the G19A polymorphism of the LEP gene affects the risk of cancer." (PMID 34868961, 2021). "In particular, a decreased adiponectin/leptin ratio predisposes patients to cancer development." (PMID 33535537, 2021). "In addition, serum leptin and leptin receptor RNA expression showed a positive association with cancer recurrence and mortality in triple-negative breast cancer." (PMID 33799880, 2021). "Leptin secretion from cancer-associated fibroblasts (CAFs) could trigger the proliferation and migration of NSCLC cells through the activation of the PI3K-AKT and MAPK-ERK signaling axes in a paracrine manner." (PMID 33799880, 2021). "In addition to its role in cell proliferation and metastasis, leptin also supports the survival of cancer cells under nutrient-deficient tumor microenvironment by promoting autophagy." (PMID 34588926, 2021). "In addition, increased levels of leptin and IL-8 seemed to be implicated in the more invasive phenotype of the cancer cells in the coculture, compared to the control." (PMID 33918733, 2021). "Then, IL-6 and leptin could represent early markers of the main symptoms and metabolic alterations associated with the pathogenesis of cancer cachexia." (PMID 33809200, 2021). "This accelerated cancer progression was accompanied by enhanced tumor-related angiogenesis and increased serum concentrations of several proinflammatory cytokines, including interleukin 6, and leptin, which suggested the potential association between MetS, inflammation, and cancer invasion." (PMID 32015762, 2020). "Leptin, a known risk factor in several kind of cancers, promotes tumor cell development." (PMID 32836215, 2020). "However, high levels of leptin and its receptor are associated with tumor progression, so it has become an important actor in cancer." (PMID 33334030, 2020). "In addition, this relationship between the cancer risk and LEP rs7799039 A>G polymorphism was reported in other meta-analyses." (PMID 33369452, 2020). "Insulin and/or leptin resistance (e.g., in obesity) may neutralize this tumor-suppressive pathway, increasing the risk of developing cancer." (PMID 32069948, 2020). "In this paper, we tested the hypothesis that leptin is associated with adiposity in SCBT in a similar way to this association in non-cancer controls." (PMID 32170116, 2020). "Leptin’s pleiotropic effects are linked to diverse processes that, if dysregulated, could contribute to the growth of cancer." (PMID 32471192, 2020). "Some previous meta-analysis showed that LEP rs7799039 polymorphism confers cancer risk." (PMID 33256658, 2020). "Recently, a meta-analysis found that a decreased risk of cancer may associate with LEP rs7799039 A>G polymorphism." (PMID 33369452, 2020). "Leptin and AdipoQ may not only be closely related to the occurrence of cancer, but closely associated with the prognosis of cancer." (PMID 33256658, 2020). "Interestingly, in obese and overweight patients, elevated levels of leptin and its ObR-b receptor are associated with increased angiogenesis, metastasis, and a poor prognosis in cancer." (PMID 33334030, 2020). "Cancer-associated fibroblasts (CAFs), the most abundant component of the tumor microenvironment in a variety of solid tumors, were recently reported to produce leptin." (PMID 31119158, 2019). "The synthesis and plasma levels of leptin increase according to total adipose tissue mass, and leptin could also be produced by cancer-associated fibroblasts." (PMID 31500658, 2019).
cancer (continued). "Leptin is one of the most important mediators between obesity and increased cancer risk." (PMID 31109060, 2019). "In solid tumours, elevated leptin level is associated with cancer risk." (PMID 31334678, 2019). "Typically, leptin is associated with increased cell proliferation in cancer." (PMID 31174326, 2019). "Although the negative regulation that obese adipose tissue associated with the tumor may cause, the exacerbated secretion of leptin by adipose tissue form may be a crucial factor for cancer progression." (PMID 31262098, 2019). "This may also explain why upon adjusting for BMI and other behavioral risk factors, the association of leptin with cancer mortality was attenuated." (PMID 29662629, 2018). "In addition, higher leptin levels in Blacks were also associated with reduced risk of cancer mortality after adjusting for confounders (adjusted HR per SD log leptin: 0.26, 95% CI: 0.13-0.51)." (PMID 29662629, 2018). "Furthermore, we found that leptin in cancer tissue was associated with that in serum (R = 0.469; P = 0.014)." (PMID 28316984, 2017). "However, there was only one study focused on the relationship between LEP rs7799039 A>G polymorphism and cancer risk in Asian populations." (PMID 29312594, 2017). "Results of meta-analyses found that both rs7799039 A>G and rs2167270 G>A polymorphisms in LEP gene might influence the risk of cancer." (PMID 29312594, 2017). "Serum leptin levels have been shown to correlate with the incidence of some cancers (breast, endometrial, colorectal, prostate), while other studies showed a lack or an inverse relation with cancer risk [21••, 30]." (PMID 29188139, 2017). "LEPR rs1137101 G>A polymorphism may alter the susceptibility of cancer by influencing the ability of binding with LEP." (PMID 29312594, 2017). "Excess body weight may be linked to increased cancer risk through changes in steroid hormones, insulin, insulin-like growth factors, leptin and adiponectin, or pro-inflammatory cytokines." (PMID 27387027, 2016). "Studies evaluating the association of leptin and cancer have largely been retrospective and may be biased due to reverse causation due to the effect of cancer-associated weight loss on leptin levels." (PMID 27636369, 2016). "However, this revealed a marked inverse association between serum leptin and risk of cancer death in women (HR: 0.81; 95% CI: 0.51–1.30 and 0.40; 95% CI: 0.51–1.30 for moderate and high compared to low levels of leptin, respectively; Ptrend = 0.0007)." (PMID 26632325, 2016). "Therefore, we examined the association of leptin with the risk of incident cancer in the multiethnic Dallas Heart Study (DHS)." (PMID 27636369, 2016). "The gender dimorphism in the leptin gene may alter leptin secretion in adipocytes and eventually alter the cancer risk in different genders." (PMID 27703473, 2016). "When considered along with upregulated signaling pathways downstream of IGF1 and leptin, and increased proliferative markers and body weight in irradiated mice, our results are suggestive of increased risk for metabolic alterations and cancer in GI tract after energetic heavy ion radiation exposure." (PMID 27558773, 2016). "As reported, in fatty population with increased risk of cancer, the level of leptin usually significantly elevated, suggesting that leptin may also be involved in cancer development." (PMID 27863383, 2016). "Interestingly vitamin D3 has been reported to inhibit leptin-mediated cancer growth by upregulating miR-498, which downregulates leptin-enhanced expression of mRNA encoding telomerase reverse transcriptase (hTERT)." (PMID 27091127, 2016). "Our study showed that leptin may be inversely associated with cancer mortality in women, and CRP corresponded with higher risk for cancer death in men." (PMID 26632325, 2016). "Leptin, one of the central adipocyte-derived hormones, has a major influence on metabolism, immune functions, and has often been associated with cell proliferation and cancer development." (PMID 26425347, 2015).